CREBRF (CREB3 regulatory factor)
Description:
Acts as a negative regulator of the endoplasmic reticulum stress response or unfolded protein response (UPR). Represses the transcriptional activity of CREB3 during the UPR. Recruits CREB3 into nuclear foci.
Synonyms: LRF; C5orf41
Tractability: No criterion of Open Targets' tractability assessment is met for any kind of drug.
Gene: Protein-coding gene on chromosome 5 (173,056,352 to 173,139,284, forward strand). Ensembl gene ENSG00000164463.
Subcellular location: Nucleus
Subcellular location (Human Protein Atlas): Nucleoplasm
Pathways (Reactome):
Cellular responses to stimuli: CREB3 factors activate genes
Gene Ontology:
Molecular function: DNA-binding transcription activator activity, RNA polymerase II-specific; protein binding; RNA polymerase II transcription regulatory region sequence-specific DNA binding; DNA-binding transcription factor activity, RNA polymerase II-specific; DNA-binding transcription factor activity
Biological process: positive regulation of transcription by RNA polymerase II; regulation of transcription by RNA polymerase II; regulation of DNA-templated transcription; response to unfolded protein
Cellular component: nucleoplasm; nucleus; nuclear body
Genetic constraint (gnomAD): Loss-of-function variants: 4 observed, 52.8 expected, observed/expected ratio (o/e) 0.0758, 90% interval 0.036 to 0.17. The synonymous counts are far from expectation, so gnomAD's model fits this gene poorly and the ratio says little. Missense variants: 475 observed, 679.1 expected, observed/expected ratio (o/e) 0.7, 90% interval 0.65 to 0.75. Synonymous variants: 189 observed, 238.94 expected, observed/expected ratio (o/e) 0.79, 90% interval 0.7 to 0.89.
Homologues: Orthologues: chimpanzee CREBRF (100% identical), macaque CREBRF (99% identical), pig CREBRF (99% identical), dog CREBRF (98% identical), rabbit CREBRF (98% identical), guinea pig CREBRF (97% identical), mouse Crebrf (94% identical), rat Crebrf (90% identical), tropical clawed frog crebrf (77% identical), zebrafish crebrf (61% identical), Drosophila melanogaster REPTOR (25% identical).
Diseases named in the same sentence as CREBRF in open-access papers:
CREBRF is named in the same sentence as 19 diseases in open-access papers, as found by Europe PMC text mining. Sharing a sentence is not in itself a finding about the gene and the disease. The quoted sentences say what the papers report.
Obesity (14 papers, 2018 to 2025). Accumulation of substantial excess body fat. "Although the CREBRF variant is predominantly found in Pacific Islanders, results from this study will also help clarify mechanisms underlying obesity-related metabolic disease risk in other high-burden populations." (PMID 41282747, 2025). "For example, a variant in CREBRF, rs373863828 (p.Arg457Gln), is associated with greater odds of obesity but lower odds of diabetes." (PMID 40108611, 2025). "The missense variant, which is located at a highly conserved position within the CREBRF gene, produced significant dose-dependent increases in obesity risk." (PMID 35159305, 2022). "Our previous study identified a nonsynonymous variant in CREBRF (rs373863828) to be strongly associated with obesity and diabetes risk in humans." (PMID 34520472, 2021). "For example, a recently reported, Polynesian-specific, CREBRF variant discovered in Samoans was strongly associated with the odds of obesity, a finding that we previously replicated in Native Hawaiians." (PMID 33571193, 2021). "Interestingly, a large-scale genomic analysis has reported that a single nucleotide variant in CREBRF is associated with obesity." (PMID 36982858, 2023). "The inability to recapitulate results of human association studies may invite reconsideration of the precise mechanistic link between CREBRF function and the risks of obesity and diabetes in variant allele carriers." (PMID 35159305, 2022). "The CREBRF variant is associated with increased BMI and increases obesity risk." (PMID 32092075, 2020). "While the genetic variant rs373863828, in CREBRF, has the largest known effect size of any identified common obesity gene, very little is currently understood about the mechanisms by which it confers increased odds of obesity but paradoxically lowered odds of type 2 diabetes." (PMID 32706746, 2020). "The CREBRF gene, involved in stress response, transcription, and its regulation, was previously identified as a key regulator of muscle energy metabolism, while variants in this gene were found to affect BMI in Samoans, a unique population with high prevalence of obesity." (PMID 40427364, 2025). "The objectives of this study were to generate a murine model with knockin of the orthologous variant in mice (CREBRFR458Q) and to test the hypothesis that this CREBRF variant promotes obesity and protects against diabetes by regulating energy and glucose homeostasis downstream of TORC1." (PMID 34520472, 2021). "Although the genetic variant rs373863828, in CREBRF, has the largest known effect size of any identified obesity gene, very little is currently understood about the mechanisms by which it confers increased odds of obesity but paradoxically lowered odds of type 2 diabetes." (PMID 32706746, 2020). "Some examples are SNVs at CREBRF and FADS1 that are associated with obesity, type 2 diabetes, and lipemic traits that are under selection in Samoans and Europeans, respectively." (PMID 36553518, 2022). "In humans, a missense variant in Creb3 regulatory factor (CREBRF) [rs373863828 (p.Arg457Gln); CREBRFR457Q] is strongly associated with increased odds of obesity but decreased odds of diabetes." (PMID 34520472, 2021). "We have separately confirmed that global deletion of murine CREBRF in mice decreases body mass and protects against diet-induced obesity, whereas global overexpression of murine CREBRF in mice has the opposite effect (Kershaw, publication in progress)." (PMID 34520472, 2021).
diabetes (8 papers, 2020 to 2026). "Uncovering the mechanism by which CREBRF impacts diabetes risk has been challenging given the need for prospective studies and long latency period before diabetes onset." (PMID 41282747, 2025). "The GROW study will characterize glucose homeostasis, diabetes progression, and the impact of a Pacific-specific variant (rs373863828) in the CREBRF gene, which is known to protect against T2DM, on glucose metabolism during and after pregnancy." (PMID 41282747, 2025). "The second major facet of the known CREBRF missense variant phenotype, namely a decreased diabetes risk, similarly seems to be poorly recapitulated in the murine model." (PMID 35159305, 2022). "The Gln allele of the CREBRF p.Arg457Gln variant associates with increased BMI but reduced risk of diabetes, the Ser allele of the IL37 p.Asn182Ser variant with gout, and the Western Polynesian-specific Leu allele of the ABCC4 p.Pro1036Leu variant with gout." (PMID 34719381, 2021). "To address critical knowledge gaps about the mechanism of action of the CREBRF variant and its biomarker and the potential therapeutic target for diabetes risk we designed the Gestational Diabetes Risk Factors and Outcomes among American Samoan Women (GROW) study." (PMID 41282747, 2025). "By integrating CGM and fs-OGTTs, this study will generate a comprehensive metabolic profile across the perinatal period, helping determine the extent to which CREBRF rs373863828 can serve as a genetic biomarker for diabetes risk and guide targeted prevention strategies for high-risk populations." (PMID 41282747, 2025). "However, the mechanisms by which CREBRF impacts diabetes risk remain unknown." (PMID 41282747, 2025).
glioblastoma (6 papers, 2016 to 2022). The most malignant astrocytic tumor (WHO grade IV). "CREBRF also serves as a tumor suppressor gene in glioblastoma as it negatively regulates cyclic-AMP-response element binding 3 (CREB3) to prevent protective autophagy in hypoxic conditions, leading to increased apoptosis." (PMID 35456993, 2022). "CREB3 regulatory factor (CREBRF), a highly conserved protein, was reportedly acted as an anti-cancer gene of glioblastoma via obstructing the hypoxia-induced autophagy." (PMID 32280304, 2020). "More recently, interleukin (IL)-6-induced autophagy has been shown in hypoxic glioblastoma cells via the p-STAT3-MIR155-3p-CREBRF pathway." (PMID 31311917, 2019). "CREBRF acts as a tumor suppressor of glioblastoma through the suppression of ATG5 and CREB3." (PMID 36358691, 2022). "In addition to suppression of growth-promoting genes, GZ17-6.02 upregulated several genes shown to inhibit the growth and invasion of glioblastoma, including BDNF-AS, CREBRF, and TLR4." (PMID 35456993, 2022).
type 2 diabetes (6 papers, 2020 to 2025). "The CREBRF rs373863828 genetic variant, which is uniquely common among Pacific Islanders, has been paradoxically associated with higher body mass index (BMI) but lower risk of type 2 diabetes." (PMID 40502564, 2025).
gastric cancer (5 papers, 2018 to 2022). A primary or metastatic malignant neoplasm involving the stomach. "As for the CREBRF gene encoding a negative regulator of the endoplasmic reticulum stress response, it can facilitate the proliferation of human gastric cancer cells and plays a central role in the progression of malignant glioma." (PMID 35682850, 2022). "Genes, such as SERPINA3, BIRC3, and CREBRF, are liable for the proliferation of various cancer cells, such as endometrial cancer and gastric cancer, but these genes may be linked with the proliferation of BRCA cells." (PMID 31311202, 2019). "CREBRF was reported to facilitate cell proliferation of gastric cancer by mediating the AKT signal pathway." (PMID 32280304, 2020). "Meanwhile, CREBRF can function as an oncogene and promote gastric cancer cell proliferation." (PMID 32092075, 2020).
gestational diabetes (3 papers, 2024 to 2025). Carbohydrate intolerance first diagnosed during pregnancy. "Genetic and epigenetic analyses will examine associations between maternal and infant CREBRF rs373863828 genotype, gestational diabetes status, infant body size, and cord blood DNA methylation." (PMID 40502564, 2025). "In Māori and Pacific adults, the CREBRF rs373863828 minor (A) allele is associated with increased body mass index (BMI) but reduced incidence of type-2 and gestational diabetes mellitus." (PMID 38627436, 2024). "However, this association was not significant after adjustment for gestational diabetes, suggesting that it may be mediated, at least in part, by the beneficial effect of CREBRF rs373863828 A allele on maternal glycemic status." (PMID 38627436, 2024).
glioma (2 papers, 2016 to 2022). A benign or malignant brain and spinal cord tumor that arises from glial cells (astrocytes, oligodendrocytes, ependymal cells). "The level of CREBRF protein was decreased significantly in MIR155-3p mimic-transfected glioma cells compared to those transfected with the negative control miRNA but increased significantly in MIR155-3p inhibitor-transfected glioma cells." (PMID 27163161, 2016). "CREB3 regulatory factor (CREBRF), a negative regulator of CREB3 (cAMP responsive element binding protein 3), contributes an important part in hypoxia-induced autophagy in glioma cells." (PMID 36071472, 2022).
autoimmune disease (1 paper, 2024). A disorder resulting from loss of function or tissue destruction of an organ or multiple organs, arising from humoral or cellular immune responses of the individual to their own tissue constituents. "CREBRF expression in PBMCs was discovered to be downregulated in polyarticular juvenile idiopathic arthritis, as well as autoimmune uveitis, which further demonstrated its clinical and therapeutic significance in autoimmune diseases." (PMID 39695085, 2024).
tumor (9 papers, 2016 to 2024). "While CREBRF suppresses tumor progression by downregulating CREB3 and ATG5, NR3C2 inhibits cancer cell survival and migration through repression of β-catenin and c-Myc." (PMID 36358691, 2022). "For example, Hsa_circ_0001947 was found to act as a tumor inhibitor to suppress the proliferation of AML cells via the hsa-miR-329-5p/CREBRF axis." (PMID 36135094, 2022). "Among the DEGs that fell into this group, there were tumor-associated genes such as GADD45A, PPM1D, PLK2 and CREBRF." (PMID 35682850, 2022). "Notably, this set contained several activated DEGs from sets of those found with cells producing uS10mut1, uS10mut2, or uS10mut3, including tumor-associated genes such as GADD45A, PPM1D, MDM2, and CREBRF." (PMID 35682850, 2022). "And the anti-tumor effect of NEAT1 on AML depended on CREBRF." (PMID 32280304, 2020). "Indeed, a number of these genes have been identified as candidate tumor suppressor genes including CREBRF, DIXDC1, AHNAK and TNS2." (PMID 28122328, 2017). "For the first time, we identified that miR124-3p and miR766-3p attenuate expression of CREBRF and NR3C2, respectively, in HNSCC, which promotes aggressive tumor behavior by inducing the signaling axes CREB3/ATG5 and β-catenin/c-Myc." (PMID 36358691, 2022). "CREBRF and NR3C2 transcriptional factors are considered tumor suppressors." (PMID 36358691, 2022).
cancer (5 papers, 2019 to 2022). A tumor composed of atypical neoplastic, often pleomorphic cells that invade other tissues. "CREB3 regulatory factor (CREBRF) is a highly conserved protein with known anti-cancer action that is down-regulated in AML patients, with significant role in migration, invasion and apoptosis of AML cells." (PMID 36362925, 2022).
metabolic disease (2 papers, 2019 to 2025). A congenital disorder (due to inherited enzyme abnormality) or acquired (due to failure of a metabolically important organ) disorder resulting from an abnormal metabolic process. "It would be interesting to determine which part of Creb3 interacts with CREBRF, whether other Creb3 family members bind CREBRF and whether mutations at the interaction site in these members are associated with metabolic diseases." (PMID 31293620, 2019).
CREBRF also shares sentences with these, for which no sentence is quoted: acute myeloid leukemia (2 papers); Alzheimer disease (1); autoimmune uveitis (1); endometrial cancer (1); gout (1); juvenile idiopathic arthritis (1); malignant glioma (1); viral infection (1).